KRAS (KRas proto-oncogene, GTPase)
Diseases named in the same sentence as KRAS in open-access papers (continued):
Sharing a sentence is not in itself a finding about the gene and the disease.
cancer (continued). "However, the distribution of KRAS variants significantly differed by cancer type." (PMID 35319967, 2022). "Therefore, we speculate that cancer recurrence cannot be predicted by KRAS mutations in ctDNA alone." (PMID 35312176, 2022). "However, as the cancer with the same potential for KRAS/BRAF mutations, the function of AHCYL1 continues to be unknown in CRC." (PMID 35578598, 2022). "Also, immune reactions to cancer cells seem to be different in KRAS-mutated CRC patients." (PMID 35884381, 2022). "Since PI3K activation is downstream of RTK–WT RAS signaling in KRAS-mutated cancer cells and cell cycle progression requires RTK/RAS signaling, these collateral dependent targets may represent a common mechanism for inhibiting MEK- and KRASG12C-inhibitor resistance." (PMID 33924994, 2021). "In other words, KRAS mutation alone may be insufficient to cause cancer." (PMID 33809880, 2021). "Thus mutant KRAS EVs could be used for rapid, non-invasive and continuous identification of cancer driver mutations, relevant for personalized treatment strategies." (PMID 33995103, 2021). "Since the Kirsten rat sarcoma viral oncogene homolog (KRAS) is mutated in about 25% of all human cancers and is at the center of pathways involved in tumorigenesis, it is necessary to compile and highlight the novel therapeutic strategies behind targeting this oncoprotein in cancer." (PMID 33801965, 2021). "Subsequent target validation revealed the dependence of KRAS-mutant cells on bioavailable intracellular Cu pools regulated by micropinocytosis; therefore, Cu-targeting drug molecules might have clinical potential in the context of KRAS-mutated cancers." (PMID 34440056, 2021). "Knockdown studies showed that the non-mutated WT RAS genes are necessary for growth-factor-mediated signaling to RAS effector pathways in HRAS-, NRAS, and KRAS-mutated cancer cells, indicating that cancer cell response to growth factors may be mediated by WT RAS, not the oncogenic RAS mutant." (PMID 33924994, 2021). "Using isogenic cells lines we could demonstrate that the introduction of an oncogenic mutation in KRAS rendered NCI-H838 cancer cells more capable of recovering from IR-induced mitochondrial shutdown and this was associated with an improved ability to remove IR-induced DNA damage foci." (PMID 34825138, 2021). "Interestingly, oncogenic KRAS mutations were shown to increase glucose uptake in cancer cells and lactate production through upregulation of glycolytic genes encoding glucose transporter SLC2A1/GLUT1 and the monocarboxylate transporters SLC16A1/MCT1, SLC16A7/MCT2, and SLC16A3/MCT4." (PMID 34003553, 2021). "Additionally, a recent breakthrough discovery on significant anticancer properties of recently approved FDA drugs, namely Sotorasib (AMG 510), in subjects with solid tumors (non-small cell lung carcinoma, colon, etc.)harboring the KRAS p.G12C mutation has shed light on cancer gene therapy." (PMID 34769370, 2021). "Likewise, identification of a novel negative genetic interaction based on frequently mutated genes (e.g., KRAS) may aid the development of new cancer therapeutic strategies." (PMID 33499282, 2021). "Thus, the profiles of KRAS mutation subtypes differ according to the type of human cancer." (PMID 34885068, 2021). "Hence, through the activation of the MAPK pathway in homeostasis state and the presence of specific mutations in cancer, KRAS seems to be at the interplay between the controlled and the uncontrolled regulation of proliferation in stem cells, possibly leading to cancer." (PMID 33691728, 2021).
cancer (continued). "Thus, our study demonstrates how combination therapies comprising KRAS G12C and FAK inhibitors achieve synergistic anticancer effects while simultaneously reducing acquired drug resistance, potentially maximizing the treatment outcomes for cancers harboring KRAS G12C mutations." (PMID 34151545, 2021). "The same may be applicable to other cancers with KRAS mutations." (PMID 34001163, 2021). "Thus, understanding molecular mechanisms may improve therapeutic strategies for cancer with KRAS and LKB1 co-mutations." (PMID 34016959, 2021). "Conversely, looking at the influence of PDAC mutations on microbiota, mutated KRAS was postulated to influence the gut and pancreatic microbiota composition and diversity, and certain host-genetic variations were proposed to cause dysbiosis and lead to cancer development." (PMID 34884776, 2021). "Since published data indicate that different KRAS mutations may give rise to different changes in cancer metabolism and phenotype, we decided to exactly address in these cell lines the O-GlcNAc level, the HBP’s enzyme expression, and the sensitivity to 2-DG and mannose treatment." (PMID 33670598, 2021). "Interestingly, KRAS-mutated cancers often highly express TRAIL and TRAIL-Rs." (PMID 32194994, 2020). "The primary wild-type organoids maintain native differentiation and 3D tissue architecture and allow mutant KRAS-targeting screening to be performed in well-defined human genetic backgrounds devoid of confounding mutations, which commonly occur in long-term passaging of 2D cancer cell lines." (PMID 32678871, 2020). "Interestingly, expression of oncogenic RAS has been shown to upregulate PD-L1 via stabilization of its mRNA19, suggesting this as a possible means by which KRAS-mutated cancers may escape immunosurveillance." (PMID 32194994, 2020). "Therefore, it is important to consider cancer therapies that target KRAS mutations." (PMID 33060649, 2020). "Besides, KRAS has been identified as an underlying treatment target for cancers." (PMID 33005174, 2020). "In support of this hypothesis, genetic or systemic IKKβ inhibition not only reduces KRAS-induced lung tumour growth by reducing cell proliferation, but also reduces KRAS-induced angiogenesis, a cancer hallmark that is associated with poor prognosis and contributes to the process of metastasis." (PMID 32823550, 2020). "Therefore, epigenetic changes associated with oncogenic KRAS expression could be an avenue where the survival of KRAS-dependent cancer cells may be vulnerable." (PMID 32576853, 2020). "Therefore, it is vital a system for targeting KRAS mutant alleles is developed, and may hold great promise for future cancer treatments." (PMID 32308773, 2020). "Thus, this approach holds great potential in treating KRAS G12S mutation-driven cancers." (PMID 32308773, 2020). "Thus, with the proviso of inhomogeneous distribution of KRAS mutation over the cancer tissue one may expect that some samples of EBC–DNA would give false negative results, although, NSCLC as a whole, harbors this mutation." (PMID 30368666, 2019). "Therefore, it is crucial to develop in silico approaches to identify the functional significant mutations that might aid in the development of cancer cells regarding the KRAS gene." (PMID 31117243, 2019). "Thus reversibility of MEKi-resistance and the consequences of MEKi withdrawal may be influenced by the nature of the particular amplified oncogene - BRAF or KRAS - highlighting again the challenges of targeting cancers with KRAS mutations." (PMID 35582726, 2019). "However, drug resistance to MEK inhibitors has been reported in cancer with KRAS mutations." (PMID 31484165, 2019). "Hence, it will be relevant to determine whether inhibiting LRP6 function interferes with tumoral properties of human KRAS-mutated cancer cells." (PMID 31412666, 2019).
cancer (continued). "Finally, these observations have some clinical correlates in that PDAC patients with higher expression levels of ORP5 or ORP8 have poorer clinical outcomes, and more generally, KRAS mutational status is associated with higher ORP5 expression across multiple cancer types." (PMID 31451509, 2019). "Diverse approaches to diagnosing and treating cancer patients has also enabled comparative effectiveness research evaluating deployment of advanced cancer therapies and associated outcomes, and utilization of KRAS and Lynch Syndrome testing to inform metastatic colorectal cancer treatment." (PMID 30972356, 2019). "As more than 30% of all human cancers, including 95% of pancreatic cancers and 45% of colorectal cancers, are driven by RAS family mutations, these amiRNAs specific to oncogenic KRAS may represent a significant breakthrough towards using miRNA drugs as personalized therapies for cancer." (PMID 31847302, 2019). "Thus, alternative approaches are needed to target KRAS-mutated cancers effectively." (PMID 31296870, 2019). "Therefore, understanding the pattern of genes co-mutated with Kras may provide novel insights into KRAS-mutant cancers with clinical implications." (PMID 31748650, 2019). "Moreover, SLC9A3 is found co-mutated with KRAS in human cancers in the TCGA database." (PMID 31748650, 2019). "We selected the mutation KRAS c.30A > C since its SynMICdb score ranked it in the 99.9th percentile and for the structural impact, RNAsnp ranked it in the 99th percentile and remuRNA in the 87th percentile, hence standing out among the cancer gene-associated synonymous mutations." (PMID 31189880, 2019). "However, a possibility of inhomogeneous distribution in cancer tissue and intratumor heterogeneity of KRAS mutation may decrease its significance." (PMID 30368666, 2019). "Moreover, human cancers in the TCGA database are prone to co-mutate KRAS and FBXW7." (PMID 31748650, 2019). "Notably, in human cancer cell lines or tumors bearing KRAS mutations, high levels of basal autophagy were observed, making inhibition of autophagy therapeutically actionable in KRAS-driven tumors." (PMID 31612108, 2019). "However, previous study has demonstrated that RAF inhibitors show little efficacy in KRAS mutant cancers, which suggests that tumors harboring KRAS mutations may be insensitive to single-agent RAF inhibitions." (PMID 31484165, 2019). "Similarly, a highly varying degree of concordance in KRAS mutational status between CTCs and primary/metastatic lesions was observed, reflecting intratumoral heterogeneity of point mutations in KRAS occurring in 48–76% of various cancers." (PMID 31635038, 2019). "Therefore, inhibition of TFEB could prevent metabolic adaptation of cancer cells to energy starvation, and thus represents a promising strategy for the treatment of cancers harboring KRAS mutations." (PMID 30400219, 2018). "Thus, the inhibition of NRF2 antioxidant and cellular detoxification program may represent a therapeutic opportunity in KRAS mutated carcinomas." (PMID 29507676, 2018). "Our limited understanding of the in vivo oncogenicities of even the most common variants of KRAS underscores the fundamental and urgent need for rapid, quantitative, and precise in vivo methods to model the diverse genetic alterations that occur in human cancers." (PMID 29233960, 2017). "However, therapeutic efficacies are low in most cancers with KRAS or BRAF mutations." (PMID 28002807, 2017).
cancer (continued). "The differential outcomes for patients with specific cancer genetics may reflect the reality that there are many phase I clinical trials of antiangiogenic-based therapeutic regimens but few studies appropriate for those with hotspot KRAS mutations." (PMID 28430579, 2017). "Consistent with this hypothesis, our findings revealed that ALK-rearranged cancer had distinctive microRNA expression profiles, while the EGFR- and KRAS-mutated cancers had similar microRNA expression profiles, despite having several differentially expressed microRNAs." (PMID 28035073, 2017). "Even if a mutation may play a major role, for example KRAS (G12D) during cancer initiation, targeting the mutation itself will be probably not effective any more once the downstream signaling pathways have been stimulated and active during cancer progression." (PMID 29177029, 2017). "Finally, the identification of increasing numbers of cancer susceptibility loci using both in vivo and in silico approaches indicate that epistatic interactions between KRAS and genetic modifiers represent another intriguing contributor to KRAS mutant oncogenicity." (PMID 29233960, 2017). "Moreover, whether KRAS status or mutations of other cancer driver genes in CRC patients (TCGA database) might have led to lack of CEACAM5 interaction with the other studied genes (CEACAM1, CEACAM6 and EPHA2) will need further investigation." (PMID 29262644, 2017). "In addition, inhibiting KRAS mutation has shown to disrupt maintenance of cancer in mice." (PMID 28381275, 2017). "Notably, despite mounting evidence that cancers harboring different KRAS mutations can have differential therapeutic responses, the singular genetic inclusion criterion of “confirmed KRAS mutation” is listed for the vast majority of clinical trials in patients with KRAS-driven tumors." (PMID 29233960, 2017). "While there are no accurate estimates of the prevalence and pathogenicity of mosaic KRAS mutations in human, it is possible that a proportion of cancer-free individuals with detectable low allelic fractions mutations in circulating DNA could reflect somatic mosaicism." (PMID 27705932, 2016). "Since the PI3K/akt/mTOR pathway and KRAS oncogene mutations all have roles in cancer cell metabolism, we investigated whether the activity of PI3K/akt/mTOR inhibitors (BEZ235 and BKM120) in cells harboring different KRAS status is related to their metabolic effect." (PMID 27283493, 2016). "In the context of cancer treatment, such a device could efficiently detect specific genetic mutations that are known to respond well to particular therapies (e.g., KRAS, HER2, EGFR, etc.), resulting in improved drug efficacy and an optimized-for-the-individual approach to treatment." (PMID 27149679, 2016). "However, KRAS mutations, which are often present in both of these carcinomas, nevertheless have the vast majority mutations on residues 12, 13 and 61 for both cancers suggesting that the mutation type may only have a small impact on the uniformity assumption." (PMID 27001666, 2016). "Interestingly, KRAS mutations are more common in smoking-associated cancers." (PMID 25514600, 2015). "However, two recent studies have uncovered what may be an Achilles’ heel for cancer cells harboring activating KRAS mutations." (PMID 26682255, 2015). "Moreover, miR-34, which is also able to suppress KRAS-driven cancer progression, could be of great benefit in patients whose acquired resistance depends on KRAS mutation." (PMID 26435742, 2015). "However, some of them failed in patients with KRAS-mutated cancers." (PMID 26168967, 2015).
cancer (continued). "Therefore, the down-regulation of cyclin D1 by resibufogenin may be also useful to overcome the resistance of MEK inhibitor in malignant tumors with mutations in both KRAS and PIK3CA." (PMID 26121043, 2015). "Activating KRAS mutation in carcinoma cells may induce angiogenesis via several mechanisms." (PMID 25888291, 2015). "One factor might be the relative sensitivity of KRAS-mutated carcinoma cells to oxaliplatin." (PMID 25888291, 2015). "Data on possible associations between KRAS mutational status and clinical and metabolic parameters, which may help in clinical management, as well as in identifying risk factors for developing these cancers, are limited in the current literature." (PMID 25158139, 2014). "Therefore whether the preponderance of KRAS mutations in cancer is linked to relative abundance of the isoforms remains an open question." (PMID 25109951, 2014). "In addition, activation of ERK1/2 can be caused by KRAS mutation in many cancer types." (PMID 24053380, 2013). "In addition, since some driver mutations are mutually exclusive, detection of specific molecular alterations might also predict resistance to specific drugs, as suggested for KRAS mutated cancers treated with EGFR tyrosine kinase inhibitors." (PMID 24236184, 2013). "Therefore, the primary goal of The Kirsten Ras In-Colorectal-Cancer Collaborative Group (RASCAL) was to definitively determine whether the presence of a KRAS mutation is of prognostic significance." (PMID 23202889, 2012). "As the association of double primary cancers and known genetic mutations has been found to be enriched in the presence of a positive family history of related cancers, we evaluated the association of the prevalence of the KRAS-variant with family history in uninformative patients." (PMID 22662244, 2012). "Based on percent spliced in (PSI) values of KRAS E4 from the TCGA SpliceSeq database, we performed a comprehensive analysis of E4 inclusion rates across 33 TCGA cancer types." (PMID 41368203, 2026). "To examine the roles of KRAS splicing isoforms in cancer progression, we first analyzed subcellular localization patterns between KRAS splicing isoforms." (PMID 41368203, 2026). "Based on this strategy, we conducted a Pearson correlation analysis between PSI values of KRAS E4 and mRNA expression levels of splicing factors across TCGA cancer tissue datasets." (PMID 41368203, 2026). "We believe that our findings broaden the current perspective on the oncogenic activity of KRAS by highlighting the role of alternative splicing and underscore its potential as a target for the development of cancer therapeutics." (PMID 41368203, 2026). "Although these findings derive from another cancer type, both cell cycle control and KRAS signalling are dysregulated in MM, making ZC3HAV1 a promising gene for further investigation in this context." (PMID 41596441, 2026). "Signaling of KRAS mutants is mostly compartmentalized to the proteolipid nanoclusters on the plasma membrane (PM), illustrating critical roles of spatiotemporal organization in KRAS cancer signaling." (PMID 42303154, 2026). "Polyisoprenylated cysteinyl amide inhibitors (PCAIs) were designed to disrupt hyperactive mutant KRAS in cancer." (PMID 42233520, 2026). "Nonetheless, these findings reinforce AURK inhibition as a promising strategy to overcome afatinib resistance in KRAS driven cancers." (PMID 41526435, 2026). "We are also exploring the development of alternative splicing-modulating agents, such as antisense oligonucleotides targeting KRAS E4 inclusion, as a potential novel anti-cancer therapeutic strategy." (PMID 41368203, 2026). "The analog BI-3706674 is currently assessed in KRASWT-amplified and KRAS-mutant cancer (NCT06056024)." (PMID 41272322, 2026).